TRMT112 (tRNA methyltransferase activator subunit 11-2)
Description:
Acts as an activator of both rRNA/tRNA and protein methyltransferases. Together with methyltransferase BUD23, methylates the N(7) position of a guanine in 18S rRNA. The heterodimer with N6AMT1/HEMK2 catalyzes N5-methylation of ETF1 on 'Gln-185', using S-adenosyl L-methionine as methyl donor. The heterodimer with N6AMT1/HEMK2 also monomethylates 'Lys-12' of histone H4 (H4K12me1). The heterodimer with ALKBH8 catalyzes the methylation of 5-carboxymethyl uridine to 5-methylcarboxymethyl uridine at the wobble position of the anticodon loop in target tRNA species. Together with methyltransferase THUMPD3, catalyzes the formation of N(2)-methylguanosine at position 6 in a broad range of tRNA substrates and at position 7 of tRNA(Trp). Involved in the pre-rRNA processing steps leading to small-subunit rRNA production. Together with methyltransferase METTL5, specifically methylates the 6th position of adenine in position 1832 of 18S rRNA.
Synonyms: HSPC152; HSPC170; TRM112; TRMT11-2; hTrm112
Tractability: Small molecule: a structure with a bound ligand is known. PROTAC: ubiquitination databases record sites on it; its protein half-life has been measured.
Gene: Protein-coding gene on chromosome 11 (64,316,460 to 64,318,074, reverse strand). Ensembl gene ENSG00000173113.
Subcellular location: Nucleus, nucleoplasm; Cytoplasm, perinuclear region
Subcellular location (Human Protein Atlas): Microtubules; Nucleoplasm
Pathways (Reactome):
Metabolism of RNA: rRNA modification in the nucleus and cytosol; tRNA modification in the nucleus and cytosol
Metabolism: Methylation
Metabolism of proteins: Eukaryotic Translation Termination
Gene Ontology:
Molecular function: protein binding; protein heterodimerization activity; protein methyltransferase activity; tRNA methyltransferase activator activity
Biological process: positive regulation of rRNA processing; rRNA (guanine-N7)-methylation; rRNA methylation; transcription initiation-coupled chromatin remodeling; tRNA methylation; tRNA wobble uridine modification; maturation of LSU-rRNA; maturation of SSU-rRNA; RNA methylation
Cellular component: cytoplasm; histone methyltransferase complex; methyltransferase complex; nucleoplasm; nucleus; perinuclear region of cytoplasm; protein-containing complex; RNA N6-methyladenosine methyltransferase complex; tRNA methyltransferase complex; cytosol; tRNA (m2G10) methyltransferase complex
Genetic constraint (gnomAD): Loss-of-function variants: 9 observed, 13.98 expected, observed/expected ratio (o/e) 0.64, 90% interval 0.39 to 1.12. The upper end of that interval is the gene's LOEUF score, 1.12, which puts it in group 4 of 6, group 1 being the genes least tolerant of losing a copy. Missense variants: 179 observed, 150.6 expected, observed/expected ratio (o/e) 1.19, 90% interval 1.05 to 1.35. Synonymous variants: 62 observed, 60.58 expected, observed/expected ratio (o/e) 1.02, 90% interval 0.83 to 1.26.
Homologues: Orthologues: chimpanzee TRMT112 (100% identical), macaque TRMT112 (99% identical), dog TRMT112 (83% identical), guinea pig TRMT112 (82% identical), mouse Trmt112 (81% identical), pig TRMT112 (81% identical), rat Trmt112 (81% identical), tropical clawed frog trmt112 (59% identical), zebrafish trmt112 (58% identical), Drosophila melanogaster Trmt112 (50% identical), Caenorhabditis elegans C04H5.1 (38% identical).
Diseases named in the same sentence as TRMT112 in open-access papers:
TRMT112 is named in the same sentence as 27 diseases in open-access papers, as found by Europe PMC text mining. Sharing a sentence is not in itself a finding about the gene and the disease. The quoted sentences say what the papers report.
pancreatic cancer (5 papers, 2022 to 2024). "For example, the altered expression of TRMT112 could affect the tumor suppressive role of WBSCR22 in pancreatic cancer (PC), leading to tumor evolution." (PMID 36226166, 2022). "Interestingly, METTL5 (a methyltransferase that specifically catalyzes 18 S rRNA N6 methylation at adenosine 1832) was considered an oncogene that promoted pancreatic cancer progression synergistically with its cofactor TRMT112 (tRNA methyltransferase activator subunit 11‐2)." (PMID 36977668, 2023). "In pancreatic cancer, TRMT112 and WBSCR22 synergistically inhibit pancreatic cancer progression by repressing ISG15 transcription, which seems to support the possibility that TRMT112 is a tumor suppressor." (PMID 39019857, 2024). "In pancreatic cancer (PAAD), the WBSCR22/TRMT112 complex downregulates the oncogene ISG15 expression, impairing malignant phenotypes." (PMID 37396662, 2023).
glioma (3 papers, 2023 to 2024). A benign or malignant brain and spinal cord tumor that arises from glial cells (astrocytes, oligodendrocytes, ependymal cells). "By analyzing the CGGA dataset, the expression of THUMPD3 in the GBM group was not significantly changed compared with that in the LGG group, while the expression of TRMT112 in the GBM group was significantly increased compared with that in the grade II glioma group." (PMID 37864150, 2023). "By analyzing CGGA dataset, the expression of TRMT112 which modifies m2G6 was significantly higher in the GBM group than that in the grade II glioma group, while the expression of TRMT10A which modifies m1G9 in the GBM group was significantly lower than that in the grade II glioma group." (PMID 37864150, 2023). "We observed the high expression levels of METLL8, METLL2A, TRMT112, METTL2B, GTPBP3, METTL6, and NSUN4 in cells in the S, G2M, and G1 phases, which were similar for astrocytes, glioma cells, and oligodendrocytes." (PMID 38824202, 2024). "rRNA m7G methylation is facilitated by Williams-Beuren syndrome chromosome region 22 (WBSCR22) and tRNA methyltransferase activator subunit 11–2 (TRMT112), while WBSCR22 fosters the glioma cell growth and metastasis by modulating the PI3K/AKT/GSK3β signaling pathway." (PMID 37964279, 2023).
breast carcinoma (2 papers, 2016 to 2026). "The dysregulation of TRMT112 across breast cancer subtypes highlights its potential as both a prognostic biomarker and a therapeutic target." (PMID 41507361, 2026). "In vivo studies using an orthotopic breast cancer model further confirmed that TRMT112 depletion impairs tumor growth and reduces metastatic burden." (PMID 41507361, 2026). "These insights provide a mechanistic foundation for future interventions aimed at targeting TRMT112-driven translational programs in aggressive breast cancer." (PMID 41507361, 2026).
Intellectual disability (2 papers, 2022 to 2024). "Furthermore, mutations in METTL5, linked to microcephaly and intellectual disability, disrupt its interaction with tRNA methyltransferase activator subunit 11−2 (TRMT112), affecting ribosomal function." (PMID 38797935, 2024). "Our work supports findings that TRMT112 is required for METTL5 stability and reveals that human METTL5 mutations associated with microcephaly and intellectual disability disrupt this interaction." (PMID 35033535, 2022).
ovarian carcinoma (2 papers, 2022 to 2024). A malignant neoplasm originating from the surface ovarian epithelium. "Results of the CPTAC data showed that TRMT112 proteins in colon cancer, ovarian cancer, and clear cell renal cell carcinoma samples were more abundant relative to that in the respective normal control (P < 0.001)." (PMID 36081672, 2022). "To explore potential drugs targeting patients in the GMPI‐high group, we collected four ovarian cancer samples and calculated GMPI for each sample with the following formula: GMPI = 0.090* KIAA0100 + 0.043* ANKRD27 + 0.215* OPA3 + 0.171* NUMBL + 0.314* PDP1–0.233*SLC7A11–0.007* TRMT112." (PMID 38506093, 2024).
brain glioma (1 paper, 2022). A malignant glioma that involves the brain. "Higher TRMT112 expression predicted poorer OS among patients with adrenocortical carcinoma (ACC, P=0.046), HNSC (P=0.0014), lower-grade brain glioma (LGG, P=0.0012), LIHC (P=0.0028), and pancreatic adenocarcinoma (PAAD, P=0.018)." (PMID 36081672, 2022).
breast invasive carcinoma (1 paper, 2022). "Additionally, a positive relationship was identified between TRMT112 expression and multiple tumor-related immune infiltrations, such as dendritic cells, CD8+ T cells, macrophages, CD4+ T cells, neutrophils, and B cells in lung adenocarcinoma and breast invasive carcinoma." (PMID 36081672, 2022).
kidney cancer (1 paper, 2024). Primary or metastatic malignant neoplasm involving the kidney. "Higher expression of TRMT112 was associated with poorer overall survival in kidney cancers (KIRC and KIRP)." (PMID 39041608, 2024).
lung squamous cell carcinomas (1 paper, 2026). "Analysis of TCGA datasets further confirmed that TRMT112 is considerably overexpressed across multiple malignancies, including breast, bladder, colon, esophageal, head and neck, renal clear cell, hepatocellular, and lung squamous cell carcinomas." (PMID 41551838, 2026).
oral cancer (1 paper, 2026). "Protein network and functional pathway enrichment analysis revealed that TRMT112 interacts with well-known oncoproteins that play a critical role in oral cancer progression." (PMID 41551838, 2026).
oral squamous cell carcinoma (1 paper, 2026). "This study aimed to investigate the expression and clinical significance of TRMT112 in patients with oral squamous cell carcinoma (OSCC)." (PMID 41551838, 2026).
prostate carcinoma (1 paper, 2021). A carcinoma that arises from epithelial cells of the prostate gland. "Some researchers analyzed the important m6A RNA regulators, which act as prognosis factors in prostate cancer, and identified RBMX, NXF1, YTHDF1, HNRNPA2B1, and TRMT112 as critical genes that have great effects on the prognosis of PCa patients." (PMID 34899855, 2021).
Williams-Beuren syndrome (1 paper, 2024). "Complexes involving METTL1 and WD repeat domain 4 (WDR4) as well as Williams-Beuren syndrome chromosome region 22 and tRNA methyltransferase activator subunit 11-2 (TRMT112) catalyze these modifications." (PMID 38798700, 2024).
tumor (14 papers, 2022 to 2026). "The upregulated expression of TRMT112 was associated with advanced tumor stages, metastasis, lower immune infiltrating levels, immunotherapy resistance, and worse prognosis." (PMID 41551838, 2026). "Analysis of the UALCAN database showed that increased expression of TRMT112 was strongly associated with the higher histological grades, advanced tumor stages, nodal metastasis, and HPV status in patients with HNSCC (P < 0.05)." (PMID 41551838, 2026). "Here, TRMT112 expression was discovered to exhibit a positive link to tumor-associated fibroblasts in BRCA, ESCA, UCEC, and COAD." (PMID 36081672, 2022). "We believe there is a valid basis for suggesting that TRMT112 could play a role in the reduced tumor immune infiltration seen in the high-risk group." (PMID 41235342, 2025). "Furthermore, TRMT112 was associated with tumor-associated fibroblasts in a variety of cancers." (PMID 36081672, 2022). "High TRMT112 expression levels showed a significant correlation with clinicopathological features, prognosis, tumor-infiltrating immune cells, and resistance to immunotherapy." (PMID 41551838, 2026). "Western blot analysis additionally validated that the levels of TRMT112 protein were significantly elevated in OSCC tissues compared to nearby non-tumor tissues." (PMID 41551838, 2026). "Among the RRMPs, tRNA methyltransferase activator subunit 11-2 (TRMT112) emerged as a key regulator of tumor progression." (PMID 41507361, 2026). "Our findings revealed that TRMT112 mRNA expression was significantly higher in OSCC tumor tissue compared to matched adjacent non-tumor samples (P < 0.0001)." (PMID 41551838, 2026). "Both datasets confirmed significantly higher TRMT112 mRNA levels in tumor tissues compared to non-tumor tissues." (PMID 41551838, 2026). "We observed significant expression of TRMT112 in malignant tumor epithelium and even higher expression in HPV+ epithelium." (PMID 41235342, 2025). "WBSCR22 has been reported to inhibit the proliferation and migration of tumor cells, and TRMT112 as its cofactor can enhance the effect of WBSCR22 as a tumor suppressor." (PMID 37710294, 2023). "Based on TCGA data, we first probed into the relation between TRMT112 and prognosis and the potential role of TRMT112 in tumor microenvironment across 33 types of tumor." (PMID 36081672, 2022). "Moreover, high TRMT112 expression was particularly linked to poorer immune-related prognosis in HPV-negative HNSCC patients, suggesting its potential role in modulating tumor–immune interactions (P = 0.01)." (PMID 41551838, 2026). "The m7G modification mediated by TRMT112 may also influence the expression of cell cycle regulatory genes, further promoting the malignant progression of tumor cells." (PMID 41235342, 2025). "The condition referred to as “cold tumor” allows tumor cells to more successfully escape detection and attacks from the immune system, which clarifies the observation that patients exhibiting high levels of TRMT112 expression tend to have less favorable outcomes with immunotherapy." (PMID 41235342, 2025). "Additionally, the m7G modification mediated by TRMT112 could facilitate tumor development and progression through the upregulation of ATF5 transcription, thereby complicating the immunotherapy landscape." (PMID 41235342, 2025). "To assess the relationship between TRMT112 expression and OSCC, we initially evaluated the mRNA levels of TRMT112 in 38 OSCC samples, along with their corresponding non-tumor tissues using qPCR." (PMID 41551838, 2026). "It is noteworthy that TRMT112 plays a crucial role in the m7G methylation process, which has been confirmed to promote the transcription of ATF5, thereby driving tumor occurrence and progression." (PMID 41235342, 2025). "Immunohistochemical staining demonstrated that TRMT112 protein expression was markedly elevated in tumor tissues compared with matched nontumor adjacent tissues (n = 5 per group)." (PMID 41235342, 2025).
tumor (continued). "Similarly, the expression of a few regulators is affected by the patients’ tumor grade, in cancers such as HNSC, KIRC, LGG, LIHC, PAAD, and UCEC; LRPPRC and TRMT112 are affected by tumor grade in most of the cancers." (PMID 39457524, 2024). "TRM112 and TRMT112 are AdoMet-dependent methyltransferases, which play a role in ribosome biogenesis and cell proliferation in both humans and S. cerevisiae, and have also been identified as being involved in tumor formation in humans." (PMID 38184845, 2024).
cancer (10 papers, 2016 to 2026). A tumor composed of atypical neoplastic, often pleomorphic cells that invade other tissues. "To discuss the molecular mechanism of TRMT112 in tumor occurrence, we combined data on TRMT112-binding protein and TRMT112 expression-associated genes in all cancers." (PMID 36081672, 2022). "Additionally, TRMT112 has been implicated in modulating RNA metabolism and transport pathways, which are essential for cancer progression." (PMID 41235342, 2025). "Collectively, our findings establish RRMPs as critical modulators of cancer progression and identify TRMT112 as a key driver of aggressive phenotypes in TNBC." (PMID 41507361, 2026). "For instance, a pancancer analysis has revealed that TRMT112 expression is positively correlated with SART1 expression in various cancers, including HNSCC." (PMID 41235342, 2025). "In HNSCC, the elevated levels of TRMT112 might facilitate the m6A modification of genes associated with tumors, which can improve their stability and translation effectiveness, ultimately leading to increased proliferation, invasion, and metastasis of cancer cells." (PMID 41235342, 2025). "The METTL5/TRMT112 complex is crucial in cancer progression, primarily through its role in rRNA modification." (PMID 38797935, 2024). "METTL5 and TRMT112 are negatively related to other genes in some cancer types, especially in OV, PRAD, BRCA, and GBM." (PMID 39457524, 2024). "In this set of genes, we also identified TRMT112 which codes for a methyltransferase known to be induced in different cancers including HCC." (PMID 37620598, 2023). "Nonetheless, it is yet unclear if TRMT112 is involved in the onset of different types of cancers via certain common molecular processes." (PMID 36081672, 2022). "Dysregulated epigenetic modifications play a critical role in cancer development where TRMT112 is a member of the transfer RNA (tRNA) methyltransferase family." (PMID 36081672, 2022). "In summary, this is the first study devoted to TRMT112 in pan-cancer, reporting increased expression of TRMT112 in a variety of tumors." (PMID 36081672, 2022). "Here, we initially explored the pan-cancer patterns of TRMT112 expression by using the TCGA project and GTEx database." (PMID 36081672, 2022). "Earlier studies have suggested that the dysregulation of TRMT112 may play a role in the advancement of cancer." (PMID 41551838, 2026). "These functions are increasingly associated with cancer development, supporting the notion that TRMT112 not only contributes to tumorigenesis but may also serve as a prognostic biomarker across multiple cancer types." (PMID 41551838, 2026). "The pathways that were found to be enriched indicate that TRMT112 could be instrumental in the development and progression of cancer, potentially collaborating with the METTL5 oncogene." (PMID 41551838, 2026). "In summary, our results suggest that TRMT112 might be a potential prognostic predictor of cancers and involved in regulating multiple cancer-related immune responses to some extent." (PMID 36081672, 2022). "Therefore, we attempted to characterize the relationship between TRMT112 and cancer development to explore its potential as a therapeutic target in cancer." (PMID 36081672, 2022). "Moreover, our findings also suggest the potential of TRMT112 as an immunomodulatory factor in cancer." (PMID 36081672, 2022). "Collectively, it was suggested that high TRMT112 expression acts as a predictor for adverse survival outcomes of cancer patients suffering from LUAD and BRCA and may be regulated by immune infiltration to some extent." (PMID 36081672, 2022). "After that, TRMT112 is a small evolutionarily conserved protein and current studies revealed that METTL5 and its partner TRMT112 are upregulated in various cancers." (PMID 38453794, 2024). "Recent studies have shed light on the role of TRMT112 in HNSCC and other cancers." (PMID 41235342, 2025).
cancer (continued). "In addition to METTL5/TRMT112 complex, NSUN5 and snoRNAs, other key regulators also play significant roles in rRNA modifications and ribosome biogenesis, significantly influence cancer progression." (PMID 38797935, 2024).
TRMT112 also shares sentences with these, for which no sentence is quoted: microcephaly (2 papers); clear cell renal cell carcinoma (1); colon cancer (1); COVID-19 (1); diffuse large B-cell lymphoma (1); liver cancer (1); lung adenocarcinoma (1); lymphoid neoplasm (1); Malignant Melanoma (1); pancreatic adenocarcinoma (1); skin cutaneous melanoma (1); thymoma (1).